PIK3CA (phosphatidylinositol-4,5-bisphosphate 3-kinase catalytic subunit alpha)
Diseases named in the same sentence as PIK3CA in open-access papers (continued):
Sharing a sentence is not in itself a finding about the gene and the disease.
cancer (continued). "Moreover, changes in the cancer methylome are coupled with somatic mutations in cancer driver genes, such as CTNNB1, ERBB2, KRAS, and PIK3CA, which consistently recapitulate the somatic evolutionary process and consequential clonality of cancers." (PMID 38566132, 2024). "While a pan-cancer epitope vaccine targeting various PIK3CA gene mutations has not been developed yet, an in vitro study focused on the H1047R point mutation, using PBMCs from healthy individuals, induced T-cell responses." (PMID 38671743, 2024). "Researchers used CRISPR-Cas9 to target the PIK3CA gene in human cancer cells." (PMID 38195537, 2024). "In addition to a crucial role in cancer progression, a paucity of discovered PIK3CA neoantigens has been noticed." (PMID 38832948, 2024). "Observations in cell lines and cancer patients led researchers to predict that miR-576-5p could down-regulate both PIK3CA and its mRNA." (PMID 38785948, 2024). "PIK3CA is a well-established oncogene, or a gene that promotes the development of cancer." (PMID 38195537, 2024). "MAP2K1 and PIK3CA expression has been observed in various cancers." (PMID 39466748, 2024). "These undesirable site effects could have compromised the therapeutic effect of targeting PIK3CA, as these mutations could activate AKT1 and thus promote cancer growth." (PMID 38195537, 2024). "Additionally, multiple de novo CTC-exclusive mutations have been identified in genes that are associated with human cancers, namely, KRAS, BRAF, and PIK3CA." (PMID 36980717, 2023). "Thus, we proposed that NEDD4L can inhibit Akt activation in ccRCC possibly through degrading its upstream activators such as STK35, SphK2, CTR1, and PIK3CA, which were previously reported in different cancers." (PMID 37580757, 2023). "Interestingly, pan-cancer analysis showed that MYC amplification is mutually exclusive with many canonical oncogenic drives such as PIK3CA, PTEN, APC, and BRAF." (PMID 37601651, 2023). "The mTOR activation mechanism in human cancers is the epigenetic and genetic alteration of the upstream signaling molecules, methylation of PTEN, mutations of Ras, PIK3CA, and PTEN, and the genetic copy gain of receptor tyrosine kinase genes and other genes in the MAP kinase and PI3K/Akt pathways." (PMID 36980552, 2023). "High-depth NGS of genomic DNA from cultured fibroblasts, using a customised panel of cancer and overgrowth-related genes, including the whole coding sequence of PIK3CA, showed no pathogenic mosaic variants." (PMID 37974153, 2023). "Also, sequencing of deep endometriotic lesions has revealed known somatic cancer driver mutations in 26% of the samples, including mutations in ARID1A and PIK3CA." (PMID 37789421, 2023).
cancer (continued). "The published results from the NCI-MATCH subprotocol Z1F of Copanlisib in PIK3CA-mutated cancer did show activity of the drug in several cancer types, but no SDC were enrolled." (PMID 37427101, 2023). "In the cohort without PIK3CA-mutated cancers, no clinically relevant treatment benefit was observed with alpelisib plus fulvestrant." (PMID 37489050, 2023). "It is well-known that PIK3CA/p110α play oncogenic role in human cancer." (PMID 37689735, 2023). "Each actor in the pathway may be concerned with different alterations (mutations, deletions, or amplifications), with PIK3CA and PTEN at the top of the list and being, respectively, the second and third most highly mutated genes in human cancers." (PMID 36900211, 2023). "Endometrial epithelia are known to harbor cancer driver mutations in the absence of any pathologies, including mutations in PIK3CA." (PMID 37170094, 2023). "Similarly, PIK3CA acquired CNVs in a wide-range of cancers which regulated the cancer progression and prognosis." (PMID 36937870, 2023). "However, new evidence suggests a crucial role of some gene mutations (PTEN, PIK3CA, FGFR2, ARID1A, and MYC) in cancer progression from endometrial hyperplasia." (PMID 38201599, 2023). "Several of the cancer-related genes we identified, including PIK3CA, KRAS, GNAS, and PPM1D, could also have haematological mutations." (PMID 37175518, 2023). "Thus, several common cancer-associated elements were monitored, demonstrating that the patterns of p-AKT, CDK1, CDK6 and PIK3CA were reduced in response to TMED3 depletion." (PMID 36991473, 2023). "The phosphatidylinositol-4,5-bisphosphate 3-kinase catalytic subunit alpha (PIK3CA) plays a fundamental role, acting in the AKT-mTOR pathway, encoding the P110α oncoprotein and regulating this cellular metabolic pathway in several human cancers." (PMID 37368773, 2023). "Furthermore, in terms of HR status subgroups, patients who harboured HR+ and PIK3CA-mutant cancer appeared to have a significantly lower pCR rate and worse DFS." (PMID 36323880, 2023). "Several ARGs showed gain of CNVs such as E2F1, MCL1, and PIK3CA across multiple cancers." (PMID 36937870, 2023). "Oncogenic PIK3CA mutations frequently occur in a higher proportion in LBC, especially in refractory advanced patients, which predicts unfavourable efficacy of immunotherapy in cancers." (PMID 37965796, 2023). "Data that clearly define an association between PIK3CA-related disorders and cancer development are limited; therefore, there is no international consensus on the appropriateness of oncological surveillance, particularly for Wilms’ tumors, in PROS patients." (PMID 38136956, 2023). "We found a total of 135 somatic PIK3CA mutations (among which 38 different mutations, located in various exomes) and 15 PIK3R1 mutations (among which 20% were considered pathogenic because loss-of-function), across 20 different cancer types." (PMID 36934165, 2023). "To verify whether CTC-like cells were truly cancer cells, we performed single-cell mutation analyses of the KRAS, BRAF, and PIK3CA genes." (PMID 36672711, 2023). "Due to PTEN depletion, PIK3CA amplification, and other genetic changes, the PI3K-Akt-mTOR pathway is most frequently overactivated in prostate cancer, which is associated with cancer progression, cancer metastasis, as well as development of drug resistance." (PMID 35296639, 2022). "By contrast, in HLA-A*03:01+ patients with cancers harboring either WT PIK3CA or a PIK3CA mutation that does not generate a public NeoAg, HLA-A LOH events were randomly divided between HLA-A*03:01 and the alternative HLA-A allele." (PMID 35484264, 2022).
cancer (continued). "In addition to detecting the PIK3CA H1047R mutation, this WGS confirmed the variant detected by the cancer gene panel in the PIK3C2B gene and demonstrated that it was germline." (PMID 35787784, 2022). "PIK3CA mutations could activate PI3K/AKT signaling and further enhance the proliferation and invasion of cancer cells, which was prevalent in GINS1 (45%)." (PMID 36345721, 2022). "Moreover, among the interaction network of cohesin subunits, many proteins are known to be involved in cancer or adenocarcinoma pathways, such as mutS homolog 6 and phosphatidylinositol-4,5-bisphosphate 3-kinase catalytic subunit alpha." (PMID 35371307, 2022). "We analyzed whether PIK3CA cancer cell fraction, the DNAcopy status, the presence of double mutations or a different proportion of mutation exons were associated with luminal subtypes." (PMID 35181669, 2022). "Similarly, of n = 44 HLA-A*03:01+ patients with a PIK3CA (E545K) cancer and an HLA-A LOH event, 23 of 44 (52.2%) lost HLA-A*03:01, whereas 21 of 44 (47.7%) lost an alternative HLA-A allele." (PMID 35484264, 2022). "PIK3CA mutation is likely to function as an oncogene in human cancers; however, its role in ICD had not been systematically investigated." (PMID 36497433, 2022). "In the second dataset, LUSC, PIK3CA (46.5%), EGFR (7%), PDE4DIP (6.6%), KRAS (4.4%), and RELN (4.4%) were labeled with copy number gain, while CDKN2A (27.9%), LRP1B (17.4%), PTEN (9.8%), and PTPRD (9%) appeared to be the cancer genes with copy number loss." (PMID 35330454, 2022). "KRAS, ARID1A, and PIK3CA are three genes, which are frequently muted in human cancers worldwide." (PMID 36072979, 2022). "Most known cancer cells have increased PIK3CA expression or more active PIK3CA which may lead to enhanced cell survivability, proliferative or anti-apoptosis ability, and overexpression of ABCB1 as we reported." (PMID 35459184, 2022). "In addition, cancer-related mutations were found in P in 18 genes, including SMAD4 (11.9%), PIK3CA (11.9%), FBXW7 (9.5%), PTEN (7.1%), and BRAF (7.1%)." (PMID 35892888, 2022). "In a cohort study of 61 patients, with two proliferative skin lesions lacking malignant potential, the typical cancer-associated PIK3CA mutations E542K, E545K and H1047R were revealed in 16% of the cases." (PMID 35317488, 2022). "The mutations commonly attributable to APOBEC mutagenesis that make the greatest contribution to cancer proliferation and survival in the most LUSC tumors are PIK3CA mutations such as E545K and E542K, a result that has previously been demonstrated only for head and neck tumors." (PMID 35872531, 2022). "We sought to determine whether PIK3CA public NeoAg-expressing tumors exhibited evidence of cancer cell-intrinsic resistance to immunologic recognition." (PMID 35484264, 2022). "Despite the key function of PI3K/AKT/mTOR activity in a sub-set of BRAF mutated colorectal cancers, few trials have attempted to target the pathway in these cancers or to systematically exploit therapeutically the sub-set with concomitant BRAF and PIK3CA mutations." (PMID 36079062, 2022). "Therefore, therascreen PIK3CA RGQ PCR Kit will be used for detection only when there are insufficient cancer tissue samples." (PMID 35735625, 2022). "If PIK3CA is not detected in the plasma ctDNA specimen, it is recommended to obtain cancer tissue specimens to clarify the PIK3CA mutation status." (PMID 38089455, 2022). "PIK3CA amplification was found to be linked with cancer relapse in patients with HNSCC, without nodal involvement." (PMID 36359251, 2022).
cancer (continued). "Prior to our study, the prognostic relevance of PIK3CA CN has been demonstrated in pan-cancer studies, but in patients with primary HR + BC one of the largest studies failed to establish an association between PIK3CA CN and outcome." (PMID 35181669, 2022). "PIK3CA mutation is usually associated with aggressive cancers that do not respond well to neoadjuvant therapy." (PMID 36387174, 2022). "The data suggest that targeting both pathways could be an effective approach to treat PIK3CA helical domain mutant cancers." (PMID 35418124, 2022). "In addition, the LAR subgroup of TNBC showed a high sensitivity to CDK4/6 inhibitors (CDK4/6i) in vitro and in vivo, and CDK4/6i sensitize PIK3CA mutant cancers to PI3Ki." (PMID 36579519, 2022). "Thus, aspirin appears to inhibit the development of Pik3ca‐mutant tumors in the laboratory mice, recapitulating its effect on PIK3CA‐mutant cancers in humans." (PMID 34245130, 2022). "In contrast, neither KRAS nor PIK3CA mutated cancers showed differences in NNMT expression relative to respective wild type tumors." (PMID 35177765, 2022). "Furthermore, a recent study also showed that high-risk HPV infections went together with mutations in PIK3CA, EP300, NF1, and RB1 in samples from benign tonsils, suggesting these mutations to be potential biomarkers to identify the cancer progression risk." (PMID 35887235, 2022). "Together, those data suggest that nuclear but not cytoplasmic p85β promotes the growth of cancer cells with a PIK3CA helical domain mutation." (PMID 35418124, 2022). "BRAF mutant cancers with wild type PIK3CA had TMB above 200 in 70% of cases." (PMID 36079062, 2022). "In addition, (phospho)proteomics study confirms that many cytoskeleton-associated proteins, e.g., β-catenin, PIK3CA, and MB21D2, are important signaling mediators, further suggesting their biofunctional roles in cancer development." (PMID 36551290, 2022). "The PIK3CA gene encodes a protein kinase that mediates signaling from insulin-like growth factor receptor IGF1R to the AKT pathway, is frequently mutated in a number of cancers, and is itself the target of several chemotherapeutic agents." (PMID 35768873, 2022). "To test this hypothesis, we stably introduced a PIK3CA activating mutation into a BRAF-mutant PTC line and assessed the impact on a number of cancer related phenotypes in vitro and in vivo." (PMID 35193694, 2022).
cancer (continued). "SMAD4 mutations show a higher prevalence in BRAF/PIK3CA double mutant cancers of the TCGA cohort but not in cancers with BRAF mutations without PIK3CA mutations." (PMID 36079062, 2022). "A recent study using next-generation sequencing technology to test cancer-related genes has shown that several targeted mutations (KRAS, PIK3CA, IRS2, Sox2, and HRR genes) may potentially become effective targeted treatment sites for patients." (PMID 35909972, 2022). "Furthermore, CDK4/6 inhibitors and PIK3CA inhibitors are standard of care for advanced luminal carcinomas, and ERBB2-low expression has been recently reported as an independent predictor of inferior progression-free survival." (PMID 36038884, 2022). "Mutations of the PIK3CA gene are found in 2% to 14% of type I endometrial cancers, and increased signaling of the PI3K/AKT/mTOR pathway is associated with a poor prognosis in both type I and type II carcinomas." (PMID 36551694, 2022). "Thus, using this NGS panel in cfDNA of mCRC patients and following ACMG and AMP guidelines, we were able to frequently identify cancer-associated variants with strong clinical significance in relevant genes, such as KRAS and PIK3CA." (PMID 34640513, 2021). "Besides, PIK3CA was abundantly expressed in many human cancers, regulating cell growth, apoptosis, and proliferation." (PMID 33996561, 2021). "Our findings indicated that these hub genes were mainly responsible for activating EMT pathways, RAS/MAPK pathways, and RTK pathways, among these other famous cancer-related pathways, which suggested that PIK3CA can exert functions in KIRC via these signaling pathways." (PMID 34367282, 2021). "Phosphatidylinositol-4,5-bisphosphate 3-kinase catalytic subunit alpha (PIK3CA) is the second most common somatic mutated gene in BC; however, the association of mutations in both genes with cancer has not been thoroughly investigated." (PMID 34287479, 2021). "GOF PIK3CA mutations deregulate the PI3K/AKT/mTOR cascade and ultimately lead to cancer formation." (PMID 34625531, 2021). "Somatic gain-of-function mutations in PIK3CA, determining a constitutive activation of the PI3K/AKT/mTOR pathway, are among the main driver mechanisms in cancer and are also responsible for benign overgrowth syndromes, collectively known as PIK3CA-related overgrowth spectrum (PROS) disorders." (PMID 34568242, 2021). "PIK3CA-mutant cancers displayed higher expression of 12 of the 17 Wnt genes compared to PIK3CA wild-type tumors, including five Wnt target genes (LEF1, MYCN, FZD7, SFRP2, and TNFRSF11B) and seven Wnt signaling components (TCF7L1, TCF7L2, CTNNB1, FZD4, SFRP1, WNT5A, and MSX2)." (PMID 34035258, 2021). "Moreover, PIK3CA, a well-known cancer-related protein, was also found to be downregulated by CDC42EP3 knockdown." (PMID 33726765, 2021). "This is supported by observations of people with disorders in the PIK3CA-related overgrowth spectrum (PROS) which is caused by the same PIK3CA mutations found in cancer, but does not feature discernible excess risk of adult malignancy." (PMID 34762647, 2021). "Silencing FSCN1 promotes apoptosis of cancer cells with PIK3CA alterations, thus enhancing radiosensitivity, and this process may be associated with the downregulation of YWHAZ." (PMID 34249689, 2021).